SLC26A4 (solute carrier family 26 member 4)
Description:
Sodium-independent transporter of chloride and iodide. Mediates electroneutral chloride-bicarbonate, chloride-iodide and chloride-formate exchange with 1:1 stoichiometry. Mediates electroneutral iodide-bicarbonate exchange (By similarity).
Synonyms: PDS; DFNB4; EVA; TDH2B
Tractability: Antibody: UniProt places it where antibodies can reach, with high confidence; its Gene Ontology location is reachable by antibodies, with high confidence; UniProt predicts a signal peptide or a membrane-spanning region. PROTAC: a small molecule that binds it is known.
Target class: SLC26 family of anion exchangers; Electrochemical transporter; SLC superfamily of solute carriers; Transporter
Safety:
Unwanted effects reported when the protein is acted on. In parentheses: how it was acted on, where the effect was seen, and who reports it.
Altered, Amphibian metamorphosis (inhibition; source: AOP-Wiki)
Gene: Protein-coding gene on chromosome 7 (107,660,594 to 107,717,809, forward strand). Ensembl gene ENSG00000091137.
Subcellular location: Cell membrane; Apical cell membrane
Pathways (Reactome):
Disease: Defective SLC26A4 causes Pendred syndrome (PDS)
Transport of small molecules: Inorganic anion exchange by SLC26 transporters
Gene Ontology:
Molecular function: chloride transmembrane transporter activity; chloride:bicarbonate antiporter activity; iodide transmembrane transporter activity; protein binding; oxalate transmembrane transporter activity; sulfate transmembrane transporter activity; secondary active sulfate transmembrane transporter activity
Biological process: iodide transport; chloride transmembrane transport; inorganic anion transport; regulation of pH; regulation of protein localization; sensory perception of sound; sulfate transmembrane transport; transmembrane transport; oxalate transport
Cellular component: apical plasma membrane; extracellular exosome; plasma membrane; brush border membrane; membrane
Genetic constraint (gnomAD): Loss-of-function variants: 50 observed, 41.44 expected, observed/expected ratio (o/e) 1.21, 90% interval 0.96 to 1.53. The upper end of that interval is the gene's LOEUF score, 1.53, which puts it in group 6 of 6, group 1 being the genes least tolerant of losing a copy. Missense variants: 710 observed, 593.07 expected, observed/expected ratio (o/e) 1.2, 90% interval 1.12 to 1.27. Synonymous variants: 247 observed, 224.1 expected, observed/expected ratio (o/e) 1.1, 90% interval 0.99 to 1.23.
Gene-disease validity (ClinGen):
ClinGen rates the evidence that SLC26A4 causes each of these diseases.
Pendred syndrome (autosomal recessive): Definitive. Pendred syndrome (PDS) is a clinically variable genetic disorder characterized by bilateral sensorineural hearing loss and euthyroid goiter.
Homologues: Orthologues: chimpanzee SLC26A4 (99% identical), macaque SLC26A4 (98% identical), pig SLC26A4 (91% identical), dog SLC26A4 (90% identical), rabbit SLC26A4 (90% identical), rat Slc26a4 (89% identical), mouse Slc26a4 (88% identical), guinea pig SLC26A4 (82% identical), tropical clawed frog slc26a4.3 (61% identical), tropical clawed frog slc26a4l (61% identical), zebrafish slc26a4 (54% identical). Paralogues in human: SLC26A3 (45% identical), SLC26A6 (36% identical), SLC26A5 (35% identical), SLC26A9 (33% identical), SLC26A2 (30% identical), SLC26A1 (27% identical), SLC26A8 (27% identical), SLC26A7 (26% identical), SLC26A11 (21% identical).
Diseases named in the same sentence as SLC26A4 in open-access papers:
SLC26A4 is named in the same sentence as 147 diseases in open-access papers, as found by Europe PMC text mining. Sharing a sentence is not in itself a finding about the gene and the disease. The quoted sentences say what the papers report.
deafness (157 papers, 2004 to 2026). An inherited or acquired condition characterized by the complete loss of the ability to hear from one or both ears. "In this study, we conducted a screening of four common deafness genes (GJB2, GJB3, mitochondrial MT-RNR1, and SLC26A4) in the Chinese population to exclude mutations in these commonly associated deafness gene loci." (PMID 39020321, 2024). "SLC26A4 is the second most mutated gene in hereditary deafness, and c.919-2A>G is a hotspot variant." (PMID 38172182, 2024). "SLC26A4 variants have been identified as the second most common cause of deafness in various populations, particularly in Asian countries." (PMID 38410152, 2024). "In 2,352 patients with non-syndromic deafness from 27 cities in China, the positivity rates of three known pathogenic sites of the SLC26A4 gene, c.919-2A > G, c.2168A > G, and c.1229C > T, were 11.52, 2.5%, and 0.51%, respectively." (PMID 38172427, 2024). "Both methods found GJB2 to be the most common deafness gene, followed by SLC26A4 and mtDNA, GJB3 variants were rare, with positive rates of 2.2%, 1.38%, 0.42%, and 0.18%, respectively, consistent with other reports." (PMID 38172182, 2024). "For example, patients with deafness associated with GJB2 or SLC26A4 have a good prognosis after cochlear implantation." (PMID 38172182, 2024). "The c.919–2A>G mutation of the SLC26A4 gene is one of the most frequent mutations causing deafness in East Asian populations." (PMID 36936679, 2023). "Mutations in the SLC26A4 gene can cause both non-syndromic (e.g., DFNB4) and syndromic (e.g., Pendred syndrome, PS) forms of deafness." (PMID 36936679, 2023). "From an epidemiological perspective, GJB2 and SLC26A4 mutations were involved in 28.5% of cases of deafness with a gene variant, while the remaining cases arose from rare gene mutations." (PMID 36597107, 2023). "The PDS gene that can cause Pendred syndrome (PDS) and non-syndromic deafness was later renamed SLC26A4 and located on chromosome 7q." (PMID 35804348, 2022). "SLC26A4 was the second most prevalent deafness-associated gene in Jiangxi Province, with the carrier rate of the screened variants accounting for nearly 32.94% (386/1,172) of all the positive samples." (PMID 36389375, 2022). "Biallelic SLC26A4 mutations lead to Pendred syndrome or DFNB4 nonsyndromic deafness, both of which are autosomal recessive." (PMID 36529647, 2022). "Genetic causes, particularly pathogenic variants in several highly prevalent deafness genes (e.g., SLC26A4, GJB2, MYO15A and OTOF) are associated with favorable CI outcomes, whereas certain imaging findings such as CND are associated with unfavorable outcomes." (PMID 36009393, 2022). "Our results highlight the differences in pathogenicity associated with certain SLC26A4 variants between transgenic mice and humans, which should be considered when interpreting the results of animal studies for SLC26A4-related deafness." (PMID 33801843, 2021). "Approximately 4–17% of deafness in patients in China is caused by SLC26A4 variants, followed by the GJB2 gene." (PMID 34276761, 2021). "The positive rate of deafness gene mutations in the Zhejiang region is higher than that of the database, mainly in GJB2c.235delC, SLC26A4 c.919-2A > G, and m.1555A > G variants." (PMID 34276761, 2021). "In conclusion, we generated a knock-in mouse model that segregated the deafness-associated SLC26A4 p.C565Y variant in humans in a genotype-driven approach." (PMID 33801843, 2021). "In summary, using a genotype-driven approach, we generated a knock-in mouse model segregating the deafness-associated SLC26A4 p.T721M variant in humans." (PMID 34697379, 2021). "PDS is the most common syndromal form of deafness and can be caused by homozygous or compound heterozygous mutation in SLC26A4, which is located on chromosome 7q22.3." (PMID 32666542, 2020). "A minor genetic variation in SLC26A4 can cause Pendred syndrome, a syndrome associated with thyroid glands and deafness." (PMID 31971949, 2020).
deafness (continued). "SLC26A4 mutations are the second‐most common cause of deafness in the Chinese mainland deaf population." (PMID 32770655, 2020). "In terms of the genetic test results, we found two genetic mutations in the proband; the SLC26A4 gene related to the syndrome type deafness with vestibular pipe expansion showed autosomal recessive inheritance." (PMID 32908492, 2020). "Avoidance of head and ear trauma in individuals with SLC26A4 mutations would dramatically reduce the incidence of deafness." (PMID 30693673, 2019). "Microsatellite haplotypes linked to SLC26A4 were investigated in 68 families presenting autosomal recessive non-syndromic deafness." (PMID 29739340, 2018). "In our previous study, MYO15A pathogenic variant was reported at a frequency of 2.1% in nonsyndromic autosomal recessive deafness, which was the fourth most common deafness gene in Korea, following SLC26A4, GJB2 and CDH23." (PMID 29482514, 2018). "PDS is thought to be one of the most common forms of syndromic deafness and pathogenic variants of SLC26A4 were reported to be the second most frequent cause of ARNSHL worldwide." (PMID 28273078, 2017). "Among a number of nonsyndromic deafness genes, variants in SLC26A4, COCH, MYO7A, GRHL2, and CLIC5 as well as POU4F3 are known to cause vestibular symptoms and/or dysfunction." (PMID 28545070, 2017). "The most common deafness gene in our cohort, SLC26A4, contained the H723R and IVS7-2A>G founder mutations, which are unique to East Asians." (PMID 26264712, 2015). "Bi-allelic GJB2 mutations were reported in 19.1% of patients with non-syndromic deafness, followed by bi-allelic SLC26A4 mutations in 12.1% and the mitochondrial MT-RNR1 mutations in 1.6%." (PMID 26011067, 2015). "In conclusion, using a genotype-driven approach, we generated a knock-in mouse model segregating the common deafness-associated SLC26A4 p.H723R mutation in humans." (PMID 23755160, 2014). "In Chinese Hans, for example, bi-allelic GJB2 mutations were reported in 19.1% of patients with non-syndromic deafness, followed by bi-allelic SLC26A4 mutations in 12.1% and the mitochondrial A1555G mutation of MT-RNR in 1.6%." (PMID 23767834, 2013). "Mutations in SLC26A4, which encodes Pendrin, are a common cause of deafness, and responsible for both syndromic and nonsyndromic hearing loss." (PMID 24341454, 2013). "Mutant mice lack Slc26a4 expression and their inner ears swell during embryonic development, which leads to failure of the cochlea and the vestibular organs resulting in deafness and loss of balance." (PMID 23874234, 2013). "Nonsyndromic inherited hearing impairment caused by mutations in GJB2, SLC26A4, or mtDNA 12S rRNA typically account for 33.8% of the cases of deafness in areas of China." (PMID 24341454, 2013). "GJB2, SLC26A4 and mitochondrial DNA (mtDNA) 12S rRNA are thought to be the most common causes of nonsyndromic autosomal recessive deafness in Asian people." (PMID 24341454, 2013). "Nonsyndromic inherited hearing impairment caused by mutations in GJB2, SLC26A4, or mtDNA 12S rRNA typical accounts for 33.8% of the cases of deafness in areas of China." (PMID 22389666, 2012). "Mutations in SLC26A4, which encodes pendrin, are a common cause of deafness, and are responsible for both syndromic and non-syndromic hearing loss." (PMID 23185506, 2012). "As previously reported, in a substantial proportion of patients our Invader techniques and additional direct sequencing revealed only one mutant GJB2 or SLC26A4 allele causing deafness by recessive pattern." (PMID 22384008, 2012). "We found a Chinese-specific SLC26A4 mutation spectrum and an associated SLC26A4 contribution to deafness." (PMID 23151025, 2012). "The molecular diagnosis of hearing impairment associated with the SLC26A4 gene is reliable because deafness is caused by homozygous or compound heterozygous SLC26A4 mutations." (PMID 23151025, 2012).
deafness (continued). "Phenotypes associated with mutations of SLC26A4 include deafness at birth and fluctuating hearing loss that progresses toward deafness during childhood." (PMID 21423764, 2011). "During inner ear development, many genes causing IEM and deafness have been identified, including SLC26A4, EYA1, FGFR3, and TCOF1." (PMID 21961810, 2011). "Mutations of SLC26A4 are found in some populations in as many as 13.7% of deaf subjects and are thereby among the most prevalent causes of deafness." (PMID 21423764, 2011). "The compatibility of SLC26A4 mutations with hearing, although limited to early childhood, provides the imperative to investigate the etiology of SLC26A4 related deafness with the ultimate goal to develop strategies to preserve hearing in afflicted individuals." (PMID 21103348, 2010). "Phenotypes associated with mutations of SLC26A4 include deafness at birth as well as fluctuating hearing loss that progresses toward deafness during childhood." (PMID 21103348, 2010). "The majority of patients bearing mutations of SLC26A4 lose hearing during early childhood - often after a period of fluctuating hearing loss that progresses toward deafness." (PMID 21103348, 2010). "It was reported that SLC26A4 mutations accounted for approximately 5% of all cases of prelingual deafness in East Asia, 5% of cases of recessive deafness in south Asia, 3.5% in the UK, and 4% in the Caucasian population with nonsyndromic hearing loss." (PMID 19744334, 2009). "In a recent publication the first human data on mutations in FOXI1 was presented demonstrating an allelic contribution to human deafness in patients heterozygotic for SLC26A4 mutations." (PMID 19214237, 2009). "Together with GJB2 (23/135), SLC26A4 are the two most commonly mutated genes causing deafness in this region." (PMID 19040761, 2008). "Pendred syndrome, an autosomal-recessive disorder characterized by deafness and goiter, is caused by a mutation of SLC26A4, which codes for the anion exchanger pendrin." (PMID 17187680, 2006). "Suppression of the KCNJ10 K+ channel in strial intermediate cells, which is essential for the generation of the endocochlear potential, is probably the direct cause of deafness in Slc26a4-/- mice and patients suffering from Pendred syndrome." (PMID 15320950, 2004). "Furthermore, we observed that the presence of additional mutations in other deafness-associated genes, such as SLC26A4 and OTOF, was associated with more severe auditory impairment." (PMID 40943139, 2025). "The frequency of deafness gene variants in descending order was SLC26A4, GJB2, GJB3, and 12S rRNA." (PMID 41181184, 2025). "However, for common hereditary deafness genes such as GJB2 and SLC26A4, the mechanisms underlying deafness are intricate and lack an efficient mouse model capable of accurately simulating disease onset." (PMID 39556694, 2024). "We then identified the spindle cells and root cells located between the stria vascularis and the outer sulcus cells, based on the expression of Slc26a4, encoding the anion exchange protein, pendrin, whose homozygous mutations cause the deafness-associated Pendred syndrome." (PMID 37339214, 2023). "The SLC26A4 pathogenic variants are the second-most common cause of deafness in China." (PMID 37107686, 2023). "SLC26A4 variants may cause his autistic phenotype, while early social competence may be overlooked by deafness." (PMID 35741772, 2022). "The aim of this study was to determine whether mutations in SLC26A4 are a frequent cause of hereditary deafness in Brazilian patients." (PMID 29739340, 2018). "In order to determine whether mutations in the SLC26A4 gene are a frequent cause of hereditary deafness in Brazilian patients, we analyzed 68 families presenting autosomal recessive non-syndromic hearing loss." (PMID 29739340, 2018).
deafness (continued). "Interestingly, a syndrome characterized by deafness and thyroid goiter (Pendred syndrome) has been associated to mutations of the related gene SLC26A4, also belonging to the same anion transporter gene family and overexpressed in thyroid." (PMID 28923001, 2017). "The distinguished mutation spectrum among different ethnical groups has also been reported for other deafness genes such as SLC26A4, in which case biallelic SLC26A4 mutations can be identified in 88.4% of deaf patients with nonsyndromic EVA in Chinese but only 15% in Caucasians." (PMID 28053790, 2016). "Nevertheless, PDS is thought to be one of the most common forms of syndromic deafness and mutations of SLC26A4 were reported to be the second most frequent cause of autosomal recessive non-syndromic sensorineural hearing loss worldwide (Hilgert, Smith & Van Camp, 2009)." (PMID 24860705, 2014). "A SLC26A4 mutation is the second most common cause of deafness in China." (PMID 24341454, 2013). "Mutations in the SLC26A4 gene may lead to autosomal-recessive deafness (DFNB4) and Pendred syndrome (non-syndromic enlarged vestibular aqueduct [NSEVA], inner ear malformation, sensorineural hearing loss, and goiter)." (PMID 22551242, 2012). "A mutation of SLC26A4 mutation is the second most common cause of deafness in China." (PMID 22389666, 2012). "Second, since deafness is associated with GJB2 and GJB3, it should be noted that the deafness associated with the SLC26A4 gene might be a consequence of digenic inheritance." (PMID 23151025, 2012). "SLC26A4 mutations are the second-most common cause of deafness in China." (PMID 23185506, 2012). "Mutations in SLC26A4, which encodes pendrin, are a common cause of deafness." (PMID 23185506, 2012). "Alternatively, SLC26A4 epigenetic modifications, such as DNA methylation, might repress gene transcription and account for the observed co-segregation of deafness and SLC26A4 monoallelic mutations." (PMID 23151025, 2012). "In our study, deafness-associated mutations in SLC26A4 were screened." (PMID 23554706, 2011). "Mutations of SLC26A4 are worldwide among the most prevalent causes of deafness." (PMID 21103348, 2010). "The frequency of SLC26A4 mutations in our nonsyndromic deafness patients is 19.3% (26/135)." (PMID 19040761, 2008). "In the present study, definite genetic diagnoses could be achieved in 18 (9.6%) of the 188 families, comprising 13 (6.9%) with bi-allelic GJB2 mutations, three (1.6%) with bi-allelic SLC26A4 mutations, and two (1.1%) with homoplasmic m.1555A>G mutations, by screening the three common deafness genes." (PMID 30576380, 2018). "Specifically, SLC26A4 pathogenic variants seem to be under-represented in this cohort, thus providing an imperative towards the investigation of additional genes and/or genomic regions that may be involved in determining deafness and EVA." (PMID 29320412, 2018). "A significant finding was the identification of 11 neonates carrying pathogenic variants in two different deafness genes (e.g., GJB2 and SLC26A4, GJB2 and 12S rRNA, etc.)." (PMID 41181184, 2025). "In Taiwan, common deafness-associated genes include GJB2, SLC26A4, OTOF, MYO15A, and MTRNR1, which were similar to those found in other populations." (PMID 40943139, 2025). "Common pathogenic mutations in patients with non-syndromic deafness in Changzhou were concentrated in GJB2 (c.235delC, c.299_300delAT, and c.176-191del16) and SLC26A4 (c.919-2A > G and c.2168 A > G)." (PMID 38172427, 2024). "It is probable that hearing loss in these patients is due to variations in other spots in the SLC26A4 gene or other deafness-related genes." (PMID 38378613, 2024). "In this study, 9 known hotspot mutations associated with the 4 most common deafness genes were investigated: GJB2 c.35delG, c.176del16, c.235delC, and c.299delAT; GJB3 c.538C>T; SLC26A4 c." (PMID 39287240, 2024).